MUC1 (mucin 1, cell surface associated)
Diseases named in the same sentence as MUC1 in open-access papers (continued):
Sharing a sentence is not in itself a finding about the gene and the disease.
cancer (continued). "This vaccine is a vector-based on the vaccinia virus, genetically modified to express the MUC1 antigen, a glycoprotein overexpressed on the surface of cancer cells, particularly in NSCLC." (PMID 41303538, 2025). "MUC1, a heterodimeric surface glycoprotein, is abnormally overexpressed in several cancers, particularly breast cancer, due to gene modifications and transcriptional dysregulation." (PMID 40069884, 2025). "In cancer, MUC-1 is often overexpressed and aberrantly glycosylated, contributing to tumor progression, metastasis, and immune evasion." (PMID 40236691, 2025). "Given the significant role of T cells, including cytotoxic T cells, in cancer immunotherapy, mice were evaluated for the presence of a MUC1-specific IFN-γ T-cell response." (PMID 40284463, 2025). "Univariate and multivariate Cox regression model for 5‐year cancer‐specific survival evaluating the prognostic independence of high cytoplasmic MUC1 expression of all carcinoma cells in lymph node metastasis." (PMID 41332218, 2025). "The upregulation of MUC1 expression is one of the downstream effects of HIF-1α activation, which is consistent with MUC-1-induced cancer cell migration and invasion." (PMID 40699805, 2025). "In cancer, MUC1 expression in particular has been found to be elevated in addition to alterations of their O-glycan structures." (PMID 41011627, 2025). "In the anodic cell, MUC1 proteins or MCF-7 cancer cells were selectively captured using anti-MUC1 antibodies immobilized on chitosan–multiwalled carbon nanotube composites." (PMID 40868803, 2025). "In the clinic, MUC1 has been widely investigated in breast cancer but is also abnormally overexpressed in various types of cancer, such as lung, pancreatic, prostate, and colon cancers." (PMID 40363817, 2025). "The prevalence of overexpressed and hypoglycosylated MUC1 in cancer cells and its accessibility on the cell surface make MUC1 a possible target for cancer vaccines." (PMID 40284463, 2025). "MUC1, a potent lipopeptic immune activator, is involved in specific immune responses and has been developed and utilized as a cancer vaccine 20-23." (PMID 39991571, 2025). "MUC-1 is a transmembrane glycoprotein that is inappropriately regulated in many types of cancer, including NSCLC, and it plays a key role in the oncogenesis of various human ADCs." (PMID 39941799, 2025). "Peptide vaccines targeting B cells with adjuvants, such as MUC1-targeting peptide vaccines, have been proven to enhance the immune response in both animal models and cancer patients by producing polyclonal antibodies." (PMID 39861694, 2025). "This sequence is part of the heavily glycosylated extracellular domain of the transmembrane protein MUC-1, which is often overexpressed and abnormally glycosylated in various cancers." (PMID 40148706, 2025). "Contrary to its protective function in healthy epithelial cells, in cancer tissues, MUC1 overexpression, together with reduced glycosylation and altered polar distribution, has a different function." (PMID 41154387, 2025). "A representative study by Tian and co-workers introduced a closed bipolar electrode-based EFC chip for the ultrasensitive and visual detection of cancer cell surface glycoprotein mucin-1 (MUC1)." (PMID 40868803, 2025). "Aptamer-based biosensors are capable of detecting not only free proteins but also MUC1 proteins on cell membranes and exosome surfaces, offering new possibilities for cancer-related research." (PMID 40363817, 2025). "In particular, clusters 9, 10, 12, 13, 14, 16, 18, 19, 21, 26, 27, 28, 30, 34 and 35 not only expressed ductal cell markers (KRT19, MMP7, TSPAN8, SOX9 and LCN2), but also expressed cancer cell markers (MUC1 and PROM1)." (PMID 40362181, 2025). "IgG increases against MUC1 and MAGE-A4 were reported in other studies and have been linked to favorable outcomes in other cancers, including NSCLC." (PMID 41228287, 2025).
cancer (continued). "Early vaccines primarily focused on TAAs such as gp100 or MUC1, which are present in both cancer cells and certain normal tissues." (PMID 40382583, 2025). "We demonstrate MARPLE's versatility across diverse targets-including anti-digoxigenin, anti-cholesterol, anti-HA, trastuzumab, and anti-MUC1-highlighting applications in infectious disease monitoring, cancer diagnostics, and therapeutic drug tracking." (PMID 41431195, 2025). "MUC1, a highly glycosylated transmembrane protein, is overexpressed and aberrantly glycosylated in many cancers, including PDAC." (PMID 40699746, 2025). "Comparison of MUC1 expression in carcinoma cells in primary CRC tumors with lymph node metastases (N+) and in lymph node (LN) metastases." (PMID 41332218, 2025). "MUC1 staining located in carcinoma cells, and stromal plasma cells served as an internal positive control." (PMID 41332218, 2025). "Interobserver agreement was primarily evaluated by scoring 10 randomly selected cases (T.T.M. and T.J.K.)for MUC1 expression in different subpopulations of carcinoma cells." (PMID 41332218, 2025). "Cribriform and solid structures had more abundant cytoplasmic and membranous MUC1 than overall carcinoma cells, while MIPs resembled overall carcinoma cells." (PMID 41332218, 2025). "Comparison of MUC1 cytoplasmic and membranous expression in all carcinoma cells and in putative anoikis‐resistant (AR) subpopulations of carcinoma cells." (PMID 41332218, 2025). "Immunohistochemical MUC1 expression was analyzed in primary tumors and nodal metastases by estimating the proportions of MUC1‐positive carcinoma cells within different subpopulations." (PMID 41332218, 2025). "We have developed anew cancer vaccinecandidate based on an MUC1-derivedGalNAc glycopeptide by replacing the threonine residue at the immunodominantepitope with (2S,3R)-3-hydroxynorvaline(Hnv)." (PMID 38274250, 2024). "MUC1 membrane mucosa is abnormally expressed in different cancers and in the stomach, it is a ligand for H. pylori and plays a key role in gastric carcinogenesis." (PMID 38463926, 2024). "In cancer, MUC1 is often dysregulated, leading to its overexpression, which significantly changes cellular behavior." (PMID 39766805, 2024). "A more recent study showed that the inhibition of MUC-1 via the WEE1 inhibitor AZD1775 can successfully suppress trastuzumab-resistant HER2+ BC with cancer stem cells (CD44high/CD24low)." (PMID 39123362, 2024). "In several cancer types, the membrane mucin MUC1 is frequently expressed as the Tn (GalNAca1-O-Ser/Thr)-glycoform, which is absent in healthy tissues." (PMID 38887285, 2024). "Numerous researchers have produced and altered CAR T cells that specifically target MUC1, and they have examined the effectiveness of these cells in various cancer models." (PMID 38611013, 2024). "Tecemotide (L-BLP25 or BLP25 Liposome Vaccine) serves as a liposomal antigen-specific cancer immunotherapeutic agent targeting mucin 1 (MUC1)." (PMID 38796455, 2024). "A cancer vaccine targeted at MUC1 not only prevents the transformation of precancerous tumors into an immunosuppressive microenvironment but also restores the body's immune surveillance against tumors." (PMID 37666495, 2024). "They observed a cluster with high expression of MUC1 and ELF3, estrogen-associated genes that influence cancer cell proliferation, migration, and invasion." (PMID 39229264, 2024). "The therapeutic potential of CAR T cells targeting Tn-MUC1 in cancer therapy is highlighted by these findings." (PMID 38611013, 2024). "MUC1 is known to be involved in cancer invasion, metastasis, and angiogenesis, through its role in intracellular signaling processes." (PMID 38707821, 2024). "Schematic illustration of the conjugation of doxorubicin and cisplatin (Dox‐Cis), followed by encapsulation within niosomes and functionalization with MUC‐1 aptamers for targeted cancer therapy." (PMID 39118454, 2024).
cancer (continued). "Among them, transmembrane protein mucin-1 (MUC1) is widely studied for its role in several kinds of cancers." (PMID 38540735, 2024). "TG4010 is a cancer vaccine expressing human MUC1 and IL-2 genes (MVA-MUC1-IL-2) composed of a highly attenuated modified Ankara virus strain." (PMID 39491020, 2024). "A specific aberrant glycoform of MUC1, which is present in approximately 95% of cancer cells, serves as a target for the development of CAR T-cell therapies, referred to as tMUC1-targeted CAR T-cells." (PMID 38612592, 2024). "Remarkably, the platform exhibited an enhanced cytotoxic effect against MUC1‐positive cancer cells compared to normal cells." (PMID 38713753, 2024). "Overexpressed MUC1 molecules in cancer cells hinders the interaction between ligands and their receptors on the cell membrane surface, reducing cell–cell interactions mediated by extracellular matrix integrins." (PMID 39491020, 2024). "Since the late 1980s, several monoclonal antibodies against MUC1 have been described and explored for the diagnosis and treatment of MUC1-overexpressing cancers." (PMID 38508723, 2024). "These included proteins associated with cancer cell biology and/or metastasis, such as LRP1, and MUC1." (PMID 39020428, 2024). "Because of its position, the C-terminus of MUC1 has been the subject of increasing research, particularly in relation to inflammation and cancer development." (PMID 38540735, 2024). "AoV cancer typically exhibits a desmoplastic stroma and commonly expresses MUC1, MUC5AC, MUC6, and MUC2." (PMID 38893239, 2024). "This study demonstrated that, the designed bis-MPA polyester dendrimer platform was highly biocompatible, specific for MUC1 overexpressing cancer cells, and significant target gene silencing ability in vitro." (PMID 38699430, 2024). "The overexpression and altered glycosylation of MUC1 in cancerous cells makes it a potentially viable candidate target for cancer immunotherapy." (PMID 38508723, 2024). "Given the putative pivotal roles of C1Q+ TAMs, CMTM2+ TANs, and MUC1+ cancer cells in mediating treatment resistance, the DREIMT tool was used to prioritize the potential drugs targeting them." (PMID 39422697, 2024). "The aberrant expression and glycosylation of MUC1 have been demonstrated in various cancers; accordingly, MUC1 is frequently used as a therapeutic marker in clinical applications." (PMID 39337716, 2024). "The MUC1 protein represents a significant target in cancer therapy due to its prevalent overexpression across various cancer types." (PMID 38713753, 2024). "Furthermore, improved targeting of proteins implicated in TNBC cancer such as folate receptor, Urokinase Plasminogen Activator Receptor, Epidermal Growth Factor Receptor, Insulin Growth Factor 1 Receptor, Wnt Pathway, Mucin 1 (MUC1), Folate Receptor and C-X-C chemokine receptor 4 (CXCR4)." (PMID 39225730, 2024). "Abnormal glycosylation of MUC is associated with cell transformation from normal to malignant phenotypes in human cancer, thus, MUC1 is the primary target for cancer vaccine design and development." (PMID 38586328, 2024). "On this basis, various MUC1-based antigens are currently being studied as vaccines for cancer treatment, with some entering clinical trial phases." (PMID 39491020, 2024). "This intricately designed platform, characterized by a diameter of 12 nm, adeptly establishes connections with MUC1‐positive MCF‐7 cancer cells." (PMID 38713753, 2024). "MUC1 engages with neutrophils and macrophages in order to safeguard cancer cells throughout the process of metastasis." (PMID 39400935, 2024). "Detecting MUC1 in fluids and performing in situ imaging of MUC1 at the cellular level are crucial for early cancer diagnosis and disease progression monitoring." (PMID 38338846, 2024). "L-BLP25 is a synthetic liposomal cancer vaccine targeting the extracellular tandem repeat sequence of the MUC1 TAA." (PMID 39491020, 2024).
cancer (continued). "This study aimed to investigate the anticancer efficacy of a conjugated drug system, consisting of doxorubicin and cisplatin (Dox‐Cis), encapsulated within niosomes and modified with MUC‐1 aptamers to enhance biocompatibility and target specific cancer cells." (PMID 39118454, 2024). "The proliferation and invasion of cancer cells were inhibited after MUC1 was eliminated, which was similar to the findings of studies of many other tumors." (PMID 38702644, 2024). "The percentage of cancer patients expressing human MUC1 varies depending on the type of cancer and the stage of the disease." (PMID 38910324, 2024). "The comprehensive delineation of mucin dysregulation in cancer now leads to a focused analysis of MUC1 and MUC16, examining their intricate molecular interactions and pivotal influence in oncological processes." (PMID 38361923, 2024). "In other cases, altered expression systems in cancer cells lead to an incompleteness in normal MUC1 glycosylation, leading to the formation of atypical side chains and an MUC1 protein which promotes disease." (PMID 38539529, 2024). "Taken together, ECs underwent phenotypically and functionally reconstructing, and MUC1+ cancer cells with high EMT activity played a key role in driving GCPM." (PMID 39422697, 2024). "The Siglec–sialylated MUC1 immune axis is a potential new target for cancer immunotherapy approaches." (PMID 38611013, 2024). "In the group demonstrating immunoresistance, heightened TGF‐β production activity was detected in MUC1+ cancer cells, and they were skewed to interplay with C1Q+ macrophages through the GDF15‐TGF‐βR2 axis." (PMID 39422697, 2024). "As a member of membrane-bound mucins, MUC1 can cross cell membranes and act as an adhesion molecule for cancer cells, contributing to extravascular metastasis of cancer cells and mediating intercellular signal transduction and adhesion." (PMID 39491020, 2024). "For instance, the MUC1 glycoprotein is overexpressed in many cancer tissues, carrying cancer-related Tn and sTn antigens (GalNAc-α-1-O-THR/SER and Neu5Acα2-6GalNAcα1-O-SER/THR, respectively)." (PMID 39594740, 2024). "Sialyl Lewis x epitope on MUC1 serves as a ligand for E-selectin, interacting with E-selectin on damaged or inflamed vascular endothelial cells, promoting adhesion between cancer cells and vascular endothelial cells." (PMID 39491020, 2024). "The MUCIN1 (MUC1) gene was identified based on its overexpression in breast and other human cancers." (PMID 38182558, 2024). "Multiple studies have suggested that MUC1 expression increases as gallbladder lesion severity progresses from hyperplasia to carcinoma in situ, whereas MUC5AC expression decreases with escalating lesion severity." (PMID 38786750, 2024). "Compared with the 2% amplification rate in the cancer genome atlas (TCGA) primary PCa cohort, the amplification of MUC1 significantly increased in the SU2C CRPC cohort (6%) and the NEPC-enriched CRPC cohort (30%)." (PMID 39491020, 2024). "The cytotoxic effects of GZMA+ CTLs on MUC1+ cancer cells through GZMA‐F2RL1 axes strengthened after immunotherapy." (PMID 39422697, 2024). "Self-antigens abnormally expressed on tumors, such as MUC1, have been targeted by therapeutic cancer vaccines." (PMID 39450169, 2024). "In the present study, we revealed that MUC1 effectively induced the proliferation and metastasis of cancer cells via the MUC1-ERK pathway." (PMID 38702644, 2024). "Secondly, the cytotoxic effects of GZMA+ CTLs on MUC1+ cancer cells augmented after immunotherapy, albeit concurrently accompanied by their increasing exhaustion." (PMID 39422697, 2024). "In different studies, 139H2 has been applied for the diagnostics of MUC1-overexpressing cancers and radioimmunotherapy." (PMID 38508723, 2024). "MUC1 is the most recognizable transmembrane protein in the mucin family and exerts a signaling function in cancer cells." (PMID 38517922, 2024).
cancer (continued). "Many studies suggest that MUC1 provides a microenvironment conducive to preventing hypoxia, acidity, and other biological conditions that promote cancer progression." (PMID 38702644, 2024). "A candidate TAA target, transmembrane glycoprotein mucin 1 (MUC1), showed strong expression in cancer cells and low expression in normal cells." (PMID 39664199, 2024). "The MUC1+ cancer cells, with the highest EMT capacity among all EC subsets, were identified as the terminally differentiated state, which also portended a dismal prognosis." (PMID 39422697, 2024). "The extracellular domain of CD66b was replaced by anti-Muc1 scFv to target Muc1 on the cancer cells." (PMID 39105847, 2024). "MUC1 was an extensively investigated biomarker in various cancer types, especially in gastrointestinal tract." (PMID 39886661, 2024). "In summary, this study recapitulates the multifaceted oncogenic role exerted by MUC1 in ccRCC and provides additional evidence that targeting MUC1 likely represents a novel therapeutic strategy for refractory cancers." (PMID 38254882, 2024). "In AoV cancer, MUC1 expression shows a connection between advanced disease stage and poor prognosis." (PMID 38893239, 2024). "There is a clear need to understand the potential impact of the production of anti-MUC1 antibodies on the T-cell response in cancer patients to modulate the T-cell response in a variety of tumors." (PMID 38164273, 2024). "MUC1 is a highly glycosylated, high-molecular-weight protein that is widely distributed on the surface of cancer cells and plays an essential role in cancer development and metastasis." (PMID 38434964, 2024). "Then, we showed that the expression of MUC1 is an important determinant of the ccRCC response to a wide range of anti-cancer drugs with distinct mode of action." (PMID 38254882, 2024). "The Cellchat algorithm further revealed the MDK‐SDC1/4 axes dominated the crosstalk between VIM+ CAFs and MUC1+ cancer cells." (PMID 39422697, 2024). "Previous studies have demonstrated that glycosylated protein MUC1 is overexpressed in breast, pancreatic, lung, and bladder cancers, underscoring its significance as a protein marker for cancer diagnosis and prognosis." (PMID 39886667, 2024). "Specifically, the MUC1+ cancer cells exhibited high TGF‐β production activity and were inclined to co‐infiltrate with C1Q+ TAMs." (PMID 39422697, 2024). "The biomarker Mucin 1 (MUC1) plays a crucial role in the metastasis and invasion of various cancer types." (PMID 38338846, 2024). "In the context of cancer, the extracellular domain of MUC1 is cleaved and released into systemic circulation wherein it appears to contribute to several intercellular signaling networks via RTK, EGFR and Akt interactions." (PMID 39020428, 2024). "The Collagen-Capan-1 transplant tumors predominantly exhibited MUC1-positive ductal cancer formation, interspersed with occasional vimentin- or α-SMA-positive fibroblasts." (PMID 38612551, 2024). "This research demonstrates the remarkable potential of aptamer-conjugated hyperbranched bis-MPA polyester-based dendritic nanoconjugates to deliver siRNAs precisely to MUC1 overexpressing cancer cells." (PMID 38699430, 2024). "The overexpression of MUC1 across various cancers makes it an ideal target for selective immunotherapies." (PMID 39886667, 2024). "This bs-Abs effectively attracted NK cells to cancer cells that had high levels of MUC-1, which in turn increased NK cells' ability to kill the cancer cells and also boosted their production of cytokines, both in in vivo and in vitro." (PMID 39609700, 2024). "In our work, we show that cancer cell MUC1 is crucial for estrogen receptor expression and activity, and for the increased capacity to form spheroids." (PMID 39349458, 2024). "In 2009, MUC1 was ranked as the second most targetable antigen to develop cancer vaccines by the National Cancer Institute33." (PMID 38326371, 2024).